VCAN (versican)
Diseases named in the same sentence as VCAN in open-access papers (continued):
Sharing a sentence is not in itself a finding about the gene and the disease.
tumor (continued). "In addition to the isoforms of versican, products from its proteolytic cleavage within the TME termed versikines are implicated in generating anti-tumour immunity." (PMID 34527586, 2021). "Since loss of the tumor suppressor DLC1 leads to increased HCC growth, we next investigated whether the newly identified target genes VCAN, TSPAN5 and CDH2 affect tumor characteristics such as proliferation or invasion." (PMID 34771537, 2021). "In the tumor microenvironment, both cancer cells and stromal cells can be a source of versican." (PMID 33708224, 2021). "With both fibronectin and versican being overexpressed in tumours this interaction may be critical for the formation of a pro-tumour matrix." (PMID 34527586, 2021). "VCAN codes for the versican protein, a structural component of the extra cellular matrix in brain cells, and is considered to be a pro-inflammatory driver of tumor progression." (PMID 33525507, 2021). "Versican expression may promote tissue stiffness in tumours and other diseases, such as sclerosis, that result in altered tissue composition." (PMID 34527586, 2021). "We found that that VCAN may be involved in tumor progression as an important ECM component through the ECM remodeling pathway as well." (PMID 33604385, 2021). "Consecuently, the production of versican or the generation of its bioactive 70-kDa versican V1 could drastically modify the outcome of the tumor." (PMID 33804223, 2021). "Overall our review suggests versican could be a component within tumours displaying an inflamed-excluded phenotype, highlighting its potential as a target for cancer immunotherapy." (PMID 34527586, 2021). "Importantly, cultured human LMS cells synthesized large quantities of versican, forming extensive pericellular coats around the tumor cells." (PMID 32265939, 2020). "A separate study showed high versican expression in the perilesional stroma of a specific subclass of ductal in situ carcinomas, and that this expression pattern was correlated to the high grade (G3) category of the tumor." (PMID 32847060, 2020). "Distinguished with VCAN and THBS2, though DCN was associated with the extracellular matrix, it could antagonize many tyrosine kinase receptors to inhibit tumor development and progression." (PMID 33200655, 2020). "For example, versican accumulation in the stroma could interfere with T cell-mediated tumor destruction by displacing the T cells from the appropriate tumor target." (PMID 32265939, 2020). "FBN1, FN1, HGF, MMP9, THBS1, and VCAN may be new GC prognostic targets by affecting tumor purity, TMB, TME score, and multiple oncogenic signaling pathways." (PMID 33014013, 2020). "Inflammation in the tumor microenvironment often contains elevated levels of versican." (PMID 32265939, 2020). "Myeloid cells are also a major source of versican in tumor inflammation." (PMID 32265939, 2020). "Besides fibroblasts, macrophages have also been demonstrated to produce versican in different murine tumor models." (PMID 31334111, 2019). "Since FTE data were available in this database, a comparison of cancer epithelium versus FTE was also included and, apart from the stromal derived candidates VCAN and SDC3, as well as MMP15, all other discovered biomarkers were associated with EOC and increased with tumour progression." (PMID 31336942, 2019). "Furthermore, TGF-β1 has been shown to up-regulate the production of versican in cancer cells and the tumor stroma, resulting in invasiveness and metastasis." (PMID 31334111, 2019). "Indeed, immune cells, mostly macrophages, have an important role in ECM remodeling, including regulation of versican levels and, consequently, tumor progression." (PMID 31334111, 2019). "Importantly, versican derived from tumor ECM activates DCs' TLR2, resulting in the production of immunosuppressive IL-10 and DC dysfunction." (PMID 31068944, 2019).
tumor (continued). "In particular, SDC3 and VCAN could be successfully replicated and were significantly overexpressed in tumour stroma compared to healthy stroma." (PMID 31336942, 2019). "Lung metastasis was correlated with versican expression in the 4T1 primary tumor." (PMID 31334111, 2019). "Thus, since versican was differentially expressed in peripheral and tumor areas, we suggest a pro-tumoral role of versican, promoting tumor progression and metastasis of the 4T1 tumor model." (PMID 31334111, 2019). "Versican is an extracellular matrix proteoglycan that is highly expressed in early development stages, with low expression remaining in adults, increasing dramatically following tissue inflammation and neoplastic diseases." (PMID 31334111, 2019). "Thus, proteolysis of versican deposited to colorectal cancer microenvironment resulted in the generation of novel matrikines and facilitated the infiltration of T cells to tumor tissues." (PMID 29559954, 2018). "High VCAN expression results in enhanced tumor invasion in gastric and cervical cancers." (PMID 29970158, 2018). "In LLC-derived tumors, both the tumor and stroma expressed versican at high levels." (PMID 29222454, 2017). "Our results suggested that macrophages which infiltrated to the tumor tissues may produce the stromal-derived versican or may bind to versican-rich ECM." (PMID 29222454, 2017). "A versican-HA complex is therefore a component of the tumor stroma." (PMID 29222454, 2017). "Furthermore, even in tumors arising from LLC cells, which express versican robustly, we observed increased Vcan mRNA levels, suggestive of a contribution of tumor microenvironment (i.e., stroma)." (PMID 29222454, 2017). "Here we investigated a potential contribution of stromal versican to tumor growth and angiogenesis." (PMID 29222454, 2017). "We next examined the contribution of stroma- derived versican in the tumor microenvironment." (PMID 29222454, 2017). "In the tumor stroma endothelial- and (myo)fibroblast-like cells displayed versican positivity." (PMID 28481899, 2017). "Notably, tumors arising from these cell lines had higher versican levels than the cell lines themselves suggesting a contribution from the host-derived tumor stroma." (PMID 29222454, 2017). "Versican functions as a tumor promoter by regulating cell-extracellular matrix interaction." (PMID 28035060, 2017). "In LLC-derived tumors, versican was produced from both tumor and stromal cells." (PMID 29222454, 2017). "Increased levels of this proteoglycan have been found in some tumors, suggesting that an increase in versican might contribute to tumor progression." (PMID 28173833, 2017). "A better understanding of the relationship between versican and cell surface receptors in spontaneous tumors in canine mammary glands may contribute to identifying new tumor progression markers." (PMID 27490467, 2016). "An explanation for this, albeit speculative, might be related to the role of VCAN in creation of a microenvironment for tumour cells." (PMID 26873137, 2016). "In immunohistochemistry analysis, neoplasms with low versican expression showed greater EGFR immunostaining in the in situ areas than in invasive areas, even as the group presenting high versican expression displayed greater EGFR and HER-2 staining in in situ areas." (PMID 27490467, 2016). "In addition to the genes discussed, there were additional stromal genes identified by the NN analysis, including CDH11, OLML3, FSTL1, AEBP1, VCAN, previously reported to correlate with tumor progression and metastasis in various cancers." (PMID 27128408, 2016). "Accordingly, increased expression of versican has been observed in neoplasias of colon and rectum." (PMID 25786261, 2015). "Versican mRNA expression was significantly greater in tumor tissues (P<0.001) than in ANT." (PMID 26619403, 2015). "The effects of stromal Versican expression on tumor progression may be dependent on the organ and tumor type examined." (PMID 26619403, 2015).
tumor (continued). "Furthermore, we chose 50 cases with both results of RT–quantitative polymerase chain reaction (qPCR) in tumor tissues and immunochemistry in paraffin sections to examine the correlation between mRNA level and protein expression of Versican." (PMID 26619403, 2015). "Versican is a ubiquitous component of the extracellular matrix and has a role in tumor progression." (PMID 26619403, 2015). "Enhanced understanding of the regulation and the involvement of versican in cancer may offer a novel approach to cancer therapy by targeting the tumor microenvironment." (PMID 25140302, 2014). "Survival analysis for versican expression in the tumor periphery revealed that in the whole study population, versican expression correlated to a longer disease-free survival (DFS), as well as a longer disease-specific survival (DSS), (P = 0.01 and P = 0.02, respectively)." (PMID 22711178, 2013). "Lack of versican expression in the epithelial cells in the tumor periphery was significantly associated with recurrent disease (P = 0.01)." (PMID 22711178, 2013). "Indeed, tumor-derived versican has been shown to activate macrophages and increase metastatic tumor growth in a model for lung carcinoma." (PMID 22643827, 2012). "Recent studies have demonstrated that LLC cells-produced factors such as versican is necessary for tumor growth and metastasis, a process that depends on TLR2-mediated myeloid cell activation, where activation of NF-κB results in inflammatory factors TNFα, IL-6 production." (PMID 23284890, 2012). "Abnormal expression of proteoglycans (PGs), such as versican, in cancer and stromal cells may serve as a biomarker for tumor progression and patient survival." (PMID 22096483, 2011). "Interestingly, there was a marked stromal decorin and versican accumulation surrounding intraductal epithelial proliferations and in situ tumor components." (PMID 21791066, 2011). "The accumulated versican in the tumor stroma supports tumor growth and metastasis." (PMID 21791066, 2011). "Enhanced understanding of the regulation and involvement of versican in cancer may offer a novel approach to cancer therapy by targeting the tumor microenvironment." (PMID 22096483, 2011). "Versican is a large HA binding proteoglycan detected in increased quantities in tumor lesions." (PMID 21541039, 2011). "Versican levels in the tumor environment can be reduced by inhibition of its production." (PMID 21541039, 2011). "Versican expression may be important during the process of tumor bony invasion and subsequent remodeling of bone that leads to osteolysis with a resultant loss in mature organized bony micro-architecture." (PMID 21079779, 2010). "Actually the terminal domains of versican may differentially control propagation of tumor cells and diversely modulate their responses to environmental hyaluronan." (PMID 21079779, 2010). "It is possible that signaling pathways associated with cell survival could also make a contribution to tumor invasion through a direct effect of versican on tumor cells." (PMID 21079779, 2010). "Versican expression is enhanced during wound repair and tumor growth." (PMID 21079779, 2010). "SFRP1 is downregulated and versican is upregulated in both tumor types." (PMID 17389037, 2007). "Versican expression may also be important during the process of tumor bony invasion and subsequent remodeling of bone that leads to osteolysis with a resultant loss in mature organized bony micro-architecture." (PMID 17662123, 2007). "The expression of versican by tumor cells themselves appears to vary." (PMID 17662123, 2007). "This suggests that versican, a molecule with properties that influence cell adhesion, may play an important role in tumor invasion." (PMID 17662123, 2007). "Versican expression may be important during the process of tumor bony invasion and subsequent remodeling of bone that leads to osteolysis." (PMID 17662123, 2007).
tumor (continued). "Furthermore, versican is involved in angiogenesis, the new blood vessel formation process that provides tumors with essential nutrients and oxygen, and regulates apoptosis which is crucial for tumor survival." (PMID 40656954, 2025). "However, VCAN-undetectable/αDPEAAE-detectable tumors demonstrated 92% of CD8+ T cells penetrating the epithelial portion of the tumor, much greater than any of the other subgroups albeit without statistical significance from VCAN-undetectable/αDPEAAE-undetectable tumors." (PMID 40361362, 2025). "Considering that these monocytes highly express SPP1 and SPP1+ Macrophages were reported to express immunoglobulin-related genes and monocyte marker VCAN, these cells might be a subset of SPP1+ Macrophages, a kind of tumor-promoting macrophage associated with unfavorable prognosis of patients." (PMID 40755770, 2025). "However, VCAN has also been shown to have pro-apoptotic effects in certain tumours." (PMID 40386063, 2025). "Hence, the high expression of VCAN in DLBCL could impact not only the TME but also tumor cell proliferation, suggesting a potential mechanism for the observed preferable prognosis." (PMID 38980810, 2024). "Therefore, VCAN+ TAMs exert pro-tumor roles through angiogenesis and inflammatory response." (PMID 39232806, 2024). "Tumor pericellular matrices with high levels of hyaluronan were found to act as barriers to immune cell migration, and there may be a similar role for VCAN expression in the epithelial zone of excluded tissues." (PMID 38517140, 2024). "This suggests that VCAN may have different functions in different tumor types." (PMID 38980810, 2024). "Moreover, we report here that tumor-expressed VCAN exhibits heterogenous structures through the combination of protein isoforms and attached CS-glycosaminoglycan (CS-GAG) sulfation patterning which associates with T-cell infiltration in both tissue analysis and in vitro models." (PMID 38517140, 2024). "The type of CS patterns determines whether VCAN supports or inhibits T-cell trafficking, and we hypothesize that targeting CS-C within the stroma could lead to the increase in T-cell migration toward tumor islands." (PMID 38517140, 2024). "In addition, versican (VCAN) is also a potential marker of anti-tumor CAFs." (PMID 36759842, 2023). "Interestingly, studies found that VCAN expression in PCa may be the source of cancer stem cell extracellular signaling cascade to initiate tumor formation." (PMID 37965470, 2023). "Additionally, researchers discovered the role of VCAN in the tumor immune microenvironment." (PMID 37461061, 2023). "However, the re-expression of VCAN in tumor cells results in its re-integration into the ECM." (PMID 37217855, 2023). "However, whether VCAN expression affected the therapeutic response to anti-tumor treatments remained unclear." (PMID 36203562, 2022). "For instance, it has been shown that an excessive expression of versican, a chondroitin sulphate proteoglycan in the stroma of cervical cancer, was significantly associated with a low number of tumour infiltrating T cells, particularly CD8+ T cell, resulting in a reduced anti-tumour immune response." (PMID 36045675, 2022). "In this review, we have focused on the role of versican in the immune response as it relates to tumour progression, with the aim of determining whether our current understanding of the immunobiology of versican warrants further study as a cancer immunotherapy target." (PMID 34527586, 2021). "Indeed, tumor cell-derived versican regulated TNF-α production in a TLR2-dependent manner." (PMID 33466303, 2021). "Whether these associations between versican expression and tumour immunity are the result of a direct role in the pathogenesis of tumours is not clear." (PMID 34527586, 2021).
tumor (continued). "We have focused here on how versican may contribute to immune-excluded tumours that have poor response to therapy and tumour-supporting innate and adaptive immune cell phenotypes, and identified two mechanisms though which this occurs, by biochemical and biophysical cues." (PMID 34527586, 2021). "Therefore, identifying the specific components of the barrier, such as versican, and understanding its structural variations in tumours can aid in developing novel approaches that may improve immunotherapy response for many people across many cancer types." (PMID 34527586, 2021). "Besides, the versican (VCAN) is also a potential marker for the tumor-repressing CAFs." (PMID 34852849, 2021). "In addition, versican may be a player in regulating the expression of PD-L1 as part of the autoimmune checkpoint involved in tumor escape from the T-cell immune response." (PMID 32265939, 2020). "Indeed, the Versican protein, released by tumor cells in the extracellular space, binds TLR2, activating multiple cell types in the tumor microenvironment, including myeloid, fibroblasts, and endothelial cells, and promotes the production of many proinflammatory cytokines." (PMID 33155039, 2020). "Thus, the proteoglycan versican may interact with leukocytes and neoplastic cells to establish a microenvironment that favors tumor expansion in the context of the 4T1 model." (PMID 31334111, 2019). "Versican has been shown to interact with myeloid and lymphoid cells in the tumor microenvironment, promoting their adhesion and production of inflammatory cytokines that may trigger the tumor invasion." (PMID 31334111, 2019). "In addition, VCAN has four subtypes, V0, V1, V2, and V3, and all of which contribute to the proliferation, adhesion, and migration of tumor cells and regulate their interaction with tumor microenvironment." (PMID 31824575, 2019). "Thus, interrupting HA-CD44 binding through VCAN may change the proteoglycan enrichment in the tumor lesion to reduce tumor growth or metastasis in cancers." (PMID 29747682, 2018). "Moreover, it is unknown what proportion of secreted lumican and versican is locally captured by the (tumor) tissue and still can be visualized by immunohistochemistry." (PMID 28481899, 2017). "Thus, tumor stroma can make a significant contribution to tumor versican content." (PMID 29222454, 2017). "Indeed, each of the tumor Western blots showed extensive versican fragmentation." (PMID 29222454, 2017). "In particular, increased expression of Versican, which has been reported in peritumoral stromal tissues, is correlated with histological tumor grade score, suggesting that this protein may be a strong factor in predicting disease relapse in lymph node-negative breast cancer patients." (PMID 26515726, 2015). "These authors therefore propose that versican may be a predictor for risk and rate of relapse, independent of tumor size in patients with node negative disease." (PMID 25140302, 2014). "Multivariate logistic regression was performed to correct for dependency between independent predictors of outcome and to investigate whether lack of versican and lumican expression in the tumor were independent risk factors for disease recurrence." (PMID 22711178, 2013). "Versican gene and protein expression is associated with mesenchymal-to-epithelial cell transition in transfected NIH 3T3 cells, and versican in extracellular matrix has been demonstrated to promote mesenchymal-to-epithelial transition of metastatic tumor cells." (PMID 23405249, 2013). "In addition, an in vivo study reveals that versican could stimulate mesenchymal to epithelial transition (MET) of metastatic tumor cells by attenuating phospho-Smad 2 levels, which result in elevated cell proliferation and accelerated metastases." (PMID 22837669, 2012). "Therefore, targeting versican synthesis may be a potential mechanism for reducing this powerful tumor-promoting agent." (PMID 22096483, 2011).